CISH (cytokine inducible SH2 containing protein)
Diseases named in the same sentence as CISH in open-access papers (continued):
Sharing a sentence is not in itself a finding about the gene and the disease.
pulmonary disease (2 papers, 2021 to 2024). "Evidence of CISH role as an inflammatory regulator was shown in a study using CISH-/- mice which had developed an increase in airway inflammation and pulmonary disease." (PMID 39676878, 2024). "It is likely that these effects on eosinophils contributes to the progressive pulmonary disease observed in CISH−/− mice." (PMID 34604264, 2021). "CISH−/− mice suffered from airway inflammation and progressively developed a pulmonary disease characterized by enhanced eosinophils within the airways and epithelial cell hyperplasia." (PMID 34604264, 2021).
Shock (2 papers, 2020 to 2021). The state in which profound and widespread reduction of effective tissue perfusion leads first to reversible, and then if prolonged, to irreversible cellular injury. "Our results suggest that genetic variations in different genes including CISH alter the activation of immune cells and, in turn, increase the risk of both early and late mortality in patients with septic shock." (PMID 34072601, 2021).
anemia (1 paper, 2023). A reduction in the number of red blood cells, the amount of hemoglobin, and/or the volume of packed red blood cells. "We hypothesized that ablation of CISH could increase susceptibility to severe malaria anemia and cerebral malaria through its impacts on erythropoiesis and/or immunity, possibly via altered inflammatory cytokine responses." (PMID 38029163, 2023).
B cell lymphomas (1 paper, 2021). "Of the screened four genes (ALCAM, CD22, CASP1, and CISH), CD22 is a sialic acid-binding immunoglobulin-like lectin (Siglec) that is highly expressed on B cell lymphomas and is a validated target for antibody and nanoparticle-based therapeutics on non-Hodgkin lymphoma." (PMID 34026619, 2021).
bacterial meningitis (1 paper, 2015). Inflammation of the membranes surrounding the brain and spinal cord due to a bacterial infection. "Most interestingly, these factors may positively (e.g., IL33 and IL18rap) and negatively (Tnfaip3, CISH and Zfp36) contribute to regulation of NF-κB, which is a hallmark feature of bacterial meningitis." (PMID 25993608, 2015).
E. coli infection (1 paper, 2022). "We found that in the stage of E. coli K1-induced BBB disruptions, α7nAChR functioned as the key regulator that affects the integrity of HBMECs by activating the JAK2–STAT5 signaling pathway, while CISH inhibited JAK2–STAT5 activation and exhibited protective effects against E. coli infection." (PMID 36289622, 2022).
egg allergy (1 paper, 2016). A food allergy that is an allergy or hypersensitivity to dietary substances from the yolk or whites of eggs, causing an overreaction of the immune system which may lead to severe physical symptoms. "Using a combination of differential gene expression and multiplex cytokine measurement, we observed that egg allergy was associated with IL-9, IL-5, and TNFα expression and secretion, as well as expression of CEACAM1, and CISH." (PMID 27788149, 2016).
fungal infection (1 paper, 2019). "The inhibitors: suppressor of cytokine signaling (SOCS) and cytokine-inducible SH2-containing protein (CIS) of the JAK/STAT signaling pathway were up-regulated, indicating that JNK and JAK/STAT signaling pathways played a limited role in defending against fungal infection." (PMID 31861642, 2019).
ischemic cardiomyopathy (1 paper, 2026). Ischemic cardiomyopathy is a cardiomyopathy in which a weakness in the muscle of the heart due to inadequate oxygen delivery to the myocardium with coronary artery disease being the most common cause. "The hub genes, including STAT3, MDM2, LRP1, IRS2, PRKCD, CCND2, and CISH, were validated to be highly expressed in adipocytes in ischemic cardiomyopathy patients with end-stage heart failure." (PMID 41869532, 2026).
leptospirosis (1 paper, 2014). A contagious bacterial infection caused by spirochetes of the genus Leptospira. "We evaluated the effect of CISH variants on leptospirosis susceptibility and the data revealed that, in heterozygosity, -292TA and + 3415CG are risk genotypes in leptospirosis cases." (PMID 25255143, 2014). "Therefore, it is strongly recommended to further investigate the role of CISH expression in leptospirosis patients." (PMID 25255143, 2014).
metastasis (1 paper, 2021). The spread or migration of cancer cells from one part of the body (where they first appeared) to another. "Moreover, SOCS1, SOCS2, and CISH were associated with lymphatic metastasis, and SOCS1-7 was associated with distant metastasis in KIRC." (PMID 34926570, 2021).
pulmonary TB (1 paper, 2024). "On the other hand, a case-control paper published in Iran found that CISH rs414171 and rs6768300 variants might be associated with protection from pulmonary TB." (PMID 39493080, 2024).
retinoblastoma (1 paper, 2019). A malignant tumor that originates in the nuclear layer of the retina. "For FISH and CISH analyses, a total of 24 retinoblastoma cases were examined, with 17 paired cases that were tested for both FISH and CISH." (PMID 31608299, 2019).
septic shock (1 paper, 2021). Shock caused by infection; frequently caused by gram negative bacteria, although some cases have been caused by other bacteria, viruses, fungi, and protozoa; characterized by fever, chills, tachycardia, tachypnea, and hypotension. "In all, these results suggest that genetic variation within the enhancer containing rs143356980 influences CISH gene expression, Jak/Stat signal transduction, and the risk of death in septic shock patients." (PMID 34072601, 2021).
triple-negative breast carcinoma (1 paper, 2022). An invasive breast carcinoma which is negative for expression of estrogen receptor (ER), progesterone receptor (PR), and human epidermal growth factor receptor 2 (HER2). "In this study, analyzing 1936 triple-negative breast cancer (TNBC) clinical samples, we highlighted correlation between CISH expression and tumor features." (PMID 35884417, 2022). "Strategies are being explored to increase the efficiency of immune checkpoint inhibitors (ICIs) targeting PD1/PDL1 in triple-negative breast cancer (TNBC), including combination with therapies inhibiting intracellular immune checkpoints such as CISH (Cytokine-induced SH2 protein)." (PMID 35884417, 2022).
tumor (119 papers, 2003 to 2026). "One autologous clinical trial (NCT05566223) uses CRISPR-Cas9 to knockout the CISH (Cytokine-induced SH2 protein) gene in tumor infiltrating lymphocytes (TILs), a type of T cell that penetrates solid tumors." (PMID 41476860, 2025). "After 3 h of incubation with modified YT–Vav1+CISH–/– and YT–Vav1+B2M–/– NK cell lines, the spheroids lost their compact structure and tumor cells detached along the edge." (PMID 40071076, 2025). "The fraction of dead tumor cells increased to ~71% for YT–Vav1+CISH–/– and to ~58% for YT–Vav1+B2M–/– (p=0.01 and p=0.025, respectively, compared to the control with no exposure)." (PMID 40071076, 2025). "Evident changes in all lifetime parameters were detected in tumor spheroids exposed to YT–Vav1+CISH–/– knockout NK cells." (PMID 40071076, 2025). "CISH knockout reprograms iPSC-derived NK cell metabolism, increases their sensitivity to IL-15 signaling, and improves in vivo persistence in tumor models." (PMID 40315330, 2025). "Combined results allowed to evaluate the efficacy of YT-Vav1+CISH–/– and YT–Vav1+B2M–/– modified NK cell lines at conditions close to tumor process development in the human body." (PMID 40071076, 2025). "Meanwhile, studies have found that SOCS1‐3 and CISH regulate immune related signals, affecting lymphocyte polarization and activation of myeloid cells, which are particularly important in the tumor microenvironment." (PMID 39307915, 2024). "This builds on previous findings that ablation of CISH improved the NK cells response to growth factors, and drastically improved the cell fitness and ability to tackle tumour cells." (PMID 39676878, 2024). "CRISPR/Cas9 knockouts of CISH in tumour-infiltrating lymphocytes (TILs) further illuminated the role of CISH and showed that its knockdown conferred the ability to combat solid tumours." (PMID 39676878, 2024). "CISH−/− iPSC-NK cells exhibit improved expansion and enhanced cytotoxic activity against various tumor cell lines under low cytokine conditions." (PMID 39682724, 2024). "In a leukemia xenograft model, CISH−/− iPSC-NK cells exhibited significantly increased in vivo persistence and tumor progression." (PMID 39682724, 2024). "Recently, we made an attempt to improve NK cell anti-tumor activity by enhancing NK cells via CISH gene knockout, based on the fact that the protein encoded by CISH is known to inhibit NK cell susceptibility to IL15 and, consequently, their cytotoxic activity." (PMID 38786032, 2024). "Deletion of CISH (a negative regulator of IL-15 signaling pathways) in iPSC-derived iNK cells can promote in vivo persistence and enhance the anti-tumor activity of the NK cells." (PMID 39664387, 2024). "For example, the deletion of Cytokine-inducible SH2-containing protein (CISH) in iPSC or CB-derived NK cells enhances in vivo persistence and anti-tumor response." (PMID 39134804, 2024). "CISH appears to serve a dual function with studies demonstrating its anti-tumour role as well as function as an inflammatory brake protein." (PMID 39676878, 2024). "For example, NK cells have been edited to delete inhibitory molecules TGFBRII (receptor for TGF-β) or cytokine-inducible SH2-containing protein (CIS) in order to enhance their anti-tumor efficacy." (PMID 39543125, 2024). "CRISPR-Cas9 mediated silencing of CISH in human NK cells enhances cytokine production capacity and NK cytotoxicity against K562 cells and improves the control of tumours in murine models." (PMID 38223411, 2024). "In tumor ovaries, CISH was examined in early and late stages (n = 14 each, all subtypes) while IL-10 and GRP78 expression were examined in early and late stage HGSC (n = 5 each)." (PMID 36830840, 2023). "In contrast, many CISH-expressing cells were located both inside the tumor (intratumor) as well as in the tumor stroma in early and late stages." (PMID 36830840, 2023). "The mechanism by which CISH in tumor cells promotes the sensitivity to Afatinib remains to be explored." (PMID 37537219, 2023).
tumor (continued). "Cytokine-inducible SH2-containing protein (CIS), encoded by CISH, is a critical negative regulator of IL-15 signaling in NK cells and a potent checkpoint in NK cell-mediated tumor immunity." (PMID 35672823, 2022). "The inhibition of CISH in mouse anti-tumor CD8 T-lymphocytes resulted in a marked increase in the ability of these lymphocytes to mediate tumor regression in vivo." (PMID 35884417, 2022). "In an AML xenograft model, CISH−/− iPSC-NK cells had an improved in vivo persistence and superior anti-tumor activity in comparison with WT iPSC-NK cells and." (PMID 35493522, 2022). "Initial studies demonstrated that deletion of CISH in mice leads to increased sensitivity to IL-15, enhanced metabolism and improved anti-tumor activity of NK cells." (PMID 35185932, 2022). "Similar work also demonstrates that deletion of CISH in PB-NK cells or UCB-NK cells can also improve their anti-tumor activity." (PMID 35185932, 2022). "CISH is a key negative regulator of IL-15 signaling in NK cells, and it inhibits anti-tumor activity of human NK cell." (PMID 36601109, 2022). "In vivo studies revealed that CISH-/- iC9/CAR19/IL-15 CB-NK cells persisted twice as long as control CAR19/IL-15 NK cells and significantly improved anti-tumor responses since animal treated with CISH KO iC9/CAR19/IL-15 CB-NK cells were tumor free." (PMID 35493522, 2022). "Combination therapies involving CISH inhibition, and BRAF as well as MEK inhibitors can extend the anti-tumor effects to additional subtypes, providing additionally opportunities for CISH modulation." (PMID 34604264, 2021). "CISH−/− NK cells additionally displayed enhanced metabolic fitness attributed to increased mTOR signaling complementing their anti-tumor activities, highlighting the multiple roles played by CISH in NK cells." (PMID 34604264, 2021). "For example, (i) CISH knockdown has been shown in increasing anti-tumour immunity by enhancing CD8+T-cell effector function." (PMID 34207299, 2021). "Lastly, modulation of CISH was found to be effective in protecting against tumor subtypes under the control of NK cells." (PMID 34604264, 2021). "The hypersensitivity of CISH−/− mice to IL-15 also enhances the anti-tumor effects of NK cells, suggesting that CISH plays a more significant role in the effector functions of NK cells rather than just their differentiation." (PMID 34604264, 2021). "CISH−/− NK cells are hypersensitive to IL-15 and, as a result, CISH−/− mice are resistant to experimental tumor metastasis." (PMID 33946954, 2021). "Nevertheless, the role of professional antigen-presenting cells like dendritic cells also cannot be circumvented for its proven role in improving anti-tumour immunity by targeting CISH." (PMID 34207299, 2021). "(ii) CISH-knockdown also increases NK-cell fitness and cytotoxicity and thus playing a crucial role in protecting tumour metastasis." (PMID 34207299, 2021). "Seminal studies demonstrated that abrogation of CISH expression on CD8+ T cells improved the anti-tumor efficacy of T cells in mouse models." (PMID 33287392, 2020). "These autologous tumor-infiltrating lymphocytes with enhanced anti-tumor efficiency are generated by knocking out the gene cytokine-inducible SH2-containing protein (CISH) via CRISPR/Cas9 in patient-derived tumor-infiltrating lymphocytes once they are collected from tumors." (PMID 41362674, 2026). "In addition to this mechanism, CD47 overexpression blocks macrophage phagocytosis, checkpoint deletions (PD-1, TIGIT) prevent tumor-mediated suppression, and CISH knockout boosts cytokine signaling and persistence in the tumor microenvironment." (PMID 41487532, 2025). "CISH limits T cell activation and signaling, so its disruption keeps anti-tumor responses high." (PMID 41476860, 2025). "The knockdown of CISH may regulate the metabolic activity of NK cells to exert an anti-tumor effect." (PMID 38898455, 2024).
tumor (continued). "Importantly, however, CISH-deleted NK cells are still sensitive to TGFβ mediated suppression and the combined suppression of both CISH and TGFβ substantially improved anti-tumour immunity compared to suppression of either protein alone." (PMID 38223411, 2024). "Although CISH is well studied in immune cells, its role in tumor cells remains poorly understood." (PMID 37537219, 2023). "CISH is a key negative regulator of IL-15 signaling in NK cells, and it plays a key role in the regulation of human NK cell metabolic activity and thereby modulates anti-tumor activity." (PMID 36601109, 2022). "CISH-knockout NK cells exhibit improved expansion and increased anti-tumor cytotoxicity." (PMID 35672823, 2022). "CISH is also a potent checkpoint in NK cell-mediated tumor immunity." (PMID 35884417, 2022). "Therefore, co-targeting CISH−/− TILs in combination with ICB-therapy would hold the potential to control tumor progression by improving the efficacy of ICB-antibodies as well as CD8+T-cell effector function." (PMID 34571899, 2021). "Thus, co-targeting CISH−/− TILs in combination with anti-PD1 antibody has proficiently controlled the tumor progression." (PMID 34571899, 2021). "However, the mechanisms of tumor-induced CISH expression are not fully understood." (PMID 36830840, 2023). "Thus, the positive association between the population of CISH-expressing cells and tumor progression suggests that induction of CISH expression may be one of the mechanisms of tumor-induced exhaustion of NK cells." (PMID 36830840, 2023). "CISH is a member of the suppressor of cytokine signaling (SOCS) family and has been shown to reduce tumor-infiltrating lymphocytes' activity against cancer through blocking their avidity." (PMID 41362674, 2026). "Genetic engineering of TILs via CRISPR/Cas9 to delete inhibitory regulators like CISH or SOCS1 has shown promise in preclinical models, leading to enhanced tumor infiltration, polyfunctionality, and complete tumor regression." (PMID 40475782, 2025). "Furthermore, they identified CISH-/- as a method to increase the vulnerability of tumours to a type of cancer immunotherapy referred to as checkpoint inhibition, using in vivo models; this later formed the basis of a clinical trial for treating certain gastrointestinal cancers using CISH-/- TIL." (PMID 39676878, 2024). "Another example is the successful engineering of cytokine-inducible SH2-containing protein (CIS) deletion in human primary NK cells using CRISPR/Cas9, which significantly enhances NK cell-mediated anti-tumor effects, particularly in GBM." (PMID 38136381, 2023). "Our objective was to document CISH expression in a large series of TNBC clinical samples and to search for correlations with tumor features and an eventual synergy with PDL1 expression." (PMID 35884417, 2022). "This can further be improved by the knockout of the IL-15 signaling regulatory protein CISH, creating iPS-NK cells with improved metabolic profile, increased expansion and persistence, and enhanced cytotoxicity in human AML xenograft tumor models." (PMID 35565395, 2022). "In vivo models have already illustrated how CISH knockout leads to TIL expansion, function, and cytokine release, as well as tumor regression." (PMID 34446084, 2021). "For instance, the sustained persistence of IL-15 in the tumor microenvironment induced the expression of the IL-15-inducible inhibitor of IL-15-signalling, namely, cytokine-inducible SH2-containing protein (CISH)." (PMID 34203391, 2021). "In turn, CISH KO resulted in increased T‐cell receptor (TCR) avidity, tumor cytolysis and neoantigen recognition." (PMID 34188916, 2021). "Cytokine-induced SH2 (CISH) protein is a member of the suppressor of cytokine signaling (SOCS) family, which is induced in CD8+ T-cells upon TCR stimulation and inhibits T-cell anti-tumor function." (PMID 34446084, 2021).